MEF2A (myocyte enhancer factor 2A)
Diseases named in the same sentence as MEF2A in open-access papers (continued):
Sharing a sentence is not in itself a finding about the gene and the disease.
gastric cancer (7 papers, 2019 to 2025). A primary or metastatic malignant neoplasm involving the stomach. "For example, epigalocatechin-3-gallate (EGCG) promotes the expression of KLF4 via MEF2A, thereby inhibiting the growth of gastric cancer cells." (PMID 37008050, 2023). "P38 MAPK activation in the gastric cancer cell line MKN45 up-regulates GLUT-4 in a MEF2A-dependent manner and promotes glucose uptake and cell growth." (PMID 37008050, 2023). "This suggests that a high expression level for MEF2A promotes the growth and metastasis of gastric cancer cells." (PMID 37008050, 2023). "In gastric cancer (GC), MEF2A promotes cancer cell proliferation and metastasis by p38MAPK phosphorylation." (PMID 37859585, 2023). "MEF2A is phosphorylated by p38MAPK in gastric cancer and promotes tumor proliferation and metastasis." (PMID 33863999, 2021). "In gastric cancer MEF-2A is phosphorylated by P38 to activate glycolysis via the GLUT-4 transporter; moreover, MEF-2A mRNA is overexpressed in 10% of tumors of patients with gastric carcinomas." (PMID 31105874, 2019). "For example, MEF2A promotes resistance to cisplatin in gastric cancer." (PMID 40592832, 2025). "Furthermore, only a few of the top twenty transcription factors identified are expressed among the gastric cancer cell lines and do not appear to be greatly affected by DCB treatment, including RARA, ATF1, THRA, and MEF2A." (PMID 41280003, 2025).
breast carcinoma (6 papers, 2019 to 2024). "Meanwhile, MEF2A has been linked to boosting tumor development and metastasis via modulating genes involved in cell proliferation and survival, indicating a bad prognosis in breast cancer patients." (PMID 39656775, 2024). "In breast cancer, MEF2A is activated by TGF-β and mediates TGF-β-induced breast cancer metastasis by upregulating MMP10." (PMID 33863999, 2021). "The top significant regulatory TFs (YY1, FOXC1, FOXL1, and MEF2A) may be responsible for the related pathways of the breast cancer cellular process of disease development." (PMID 39656775, 2024). "In breast cancer (BC), MEF2A induced tumour metastasis by affecting MMP10 expression." (PMID 37859585, 2023). "MEF2A is negatively regulated in four sets of lung cancer and in the PAH set, and positively regulated in one set of breast cancer and in two of leukemia." (PMID 36101460, 2022).
heart failure (6 papers, 2017 to 2024). Inability of the heart to pump blood at an adequate rate to meet tissue metabolic requirements. "In terms of cardiac gene expression, MEF2A is of particular interest since MEF2A homozygous null mice are prone to perinatal sudden death within a week due to heart failure, characterized by ventricular dilation, myofibrillar disorganization and disordered mitochondria." (PMID 37019881, 2023). "We provide a better understanding of the molecular mechanisms underlying this interaction may contribute to the development of novel therapeutic strategies targeting HDAC5 and MEF2A for the treatment of heart failure and other cardiovascular diseases." (PMID 37667300, 2023). "Despite its global impact on cardiac mRNA splicing, the RBFOX1-mediated isoform switch (α1 versus α2) of MEF2 genes (MEF2A, MEF2C and MEF2D) appears to be a crucial regulatory circuit contributing to the development of heart failure." (PMID 39045460, 2024). "HDAC4 prevents effective DNA binding by myocyte enhancer factor 2A (MEF2A, MEF2), contributing to hypertrophic gene expression and heart failure." (PMID 37326902, 2023).
cardiomyopathy (5 papers, 2016 to 2023). A disease of the heart muscle or myocardium proper. "Among the cardiomyopathy, we further found that the inhibition of MEF2A in iPSC-CMs resulted in significant change of gene expression associated with electrophysiological abnormalities." (PMID 36653336, 2023). "Consistent with the cardiomyopathy phenotype and enhanced MEF2 activity in adult MEF2A-deficient hearts, miR-410 and miR-495 were found to be significantly upregulated." (PMID 26999812, 2016). "Unlike perinatal MEF2A-deficient hearts, adult mutant mice do not display cardiomyocyte myofibrillar defects but instead develop a form of adult onset cardiomyopathy characterized by mitochondrial deficiency and conduction defects." (PMID 26999812, 2016).
Insulin resistance (5 papers, 2013 to 2021). Increased resistance towards insulin, that is, diminished effectiveness of insulin in reducing blood glucose levels. "Expression of MEF2A is downregulated in lesional skin samples which suggests a possible mechanism for insulin resistance in psoriasis." (PMID 24303025, 2013). "AR can be an important link between inflammation and insulin resistance, while MEF2A has role in insulin signaling." (PMID 24303025, 2013). "Glucosamine-induced ER stress causes insulin resistance in both human and rat skeletal muscle and impairs GLUT4 production and insulin-induced glucose uptake via an ATF6α-dependent decrease of the GLUT4 regulators MEF2A and PGC1α." (PMID 23716639, 2013). "Collectively, we conclude that PIMT mediates TNF-α induced insulin resistance at the skeletal muscle via the transcriptional modulation of GLUT4, MEF2A, PGC-1α and HDAC5 genes." (PMID 26468734, 2015).
Alzheimer disease (4 papers, 2021 to 2023). A progressive, neurodegenerative disease characterized by loss of function and death of nerve cells in several areas of the brain leading to loss of cognitive function such as memory and language. "Hypermethylation of the MEF2A promoter or genetic variants in MEF2A exons have been linked to Alzheimer's disease." (PMID 37008050, 2023). "Alzheimer’s disease is also characterized by downregulation of autophagy-related-genes that are regulated by MEF2A." (PMID 36834528, 2023).
colorectal cancer (4 papers, 2021 to 2025). A primary or metastatic malignant neoplasm that affects the colon or rectum. "Research have demonstrated a substantial link between abnormal MEF2A expression and the progression of various tumor types, including colorectal cancer, hepatocellular carcinoma, and large B‐cell lymphoma." (PMID 40066751, 2025). "For example, MEF2A promoted tumor proliferation and metastasis by transcriptionally upregulating the expression of ZEB2 and CTNNB1 in colorectal cancer." (PMID 40066751, 2025). "Another study elucidated that MEF2A could directly upregulate CTNNB1 and enhance the activity of Wnt/β-catenin signaling in colorectal cancer." (PMID 35477537, 2022).
hepatocellular carcinoma (4 papers, 2015 to 2024). A malignant tumor that arises from hepatocytes. "A previous study has demonstrated that the activation of HIF-1A-FOX3 and MEF2A pathways can induce apoptosis in hepatocellular carcinoma cells." (PMID 38542784, 2024). "MEF2A and -C mRNA and protein abundance tended to be greater in hepatocellular carcinoma (HCC) cells than normal liver cells and MEF2D expression in HCC patient samples was associated with poor prognosis." (PMID 26506234, 2016). "MEF2A was previously found to promote epithelial‐mesenchymal transition (EMT) and invasiveness of hepatocellular carcinoma." (PMID 31215771, 2019). "As MEF2A, -C and -D promoted EMT of hepatocellular carcinoma cells, they may also promote EMT of the neural crest cells." (PMID 26506234, 2016).
hypertrophic cardiomyopathy (4 papers, 2012 to 2025). A condition in which the myocardium is hypertrophied without an obvious cause. "Several SNPs identified in the human MEF2A gene were reported to be associated with hypertrophic cardiomyopathy and coronary artery disease." (PMID 29549288, 2018). "MEF2A is a key nuclear mediator that may participate in the pathological remodeling and accumulation of focal fibrosis in hypertrophic cardiomyopathy." (PMID 27105518, 2016).
lung carcinoma (4 papers, 2016 to 2024). "In the lung cancer group from TCGA, high expression of MEF2A was significantly associated with increased DSS and PFI of patients." (PMID 37394466, 2023).
ovarian carcinoma (4 papers, 2020 to 2022). A malignant neoplasm originating from the surface ovarian epithelium. "Additionally, in ovarian cancer, MEF2A was considered one of the transcription factors (TFs) responding to norepinephrine-involving tumorigenesis." (PMID 33863999, 2021). "In ovarian cancer, the expression of TAP1 is related to MEF2A, LEF1, while MEF2A can promote tumor cell metastasis by inducing epithelial-mesenchymal transformation and activating Wnt/β-catenin signal pathway." (PMID 36419887, 2022). "Further, we verified the expression of TAP1-related transcription factors (MEF2A and LEF1) and found that TAP1 was closely related to ovarian cancer metastasis in vitro and in vivo." (PMID 34957213, 2021).
Parkinson disease (4 papers, 2021 to 2023). A progressive degenerative disorder of the central nervous system characterized by loss of dopamine producing neurons in the substantia nigra and the presence of Lewy bodies in the substantia nigra and locus coeruleus. "Halting the degradation of the ubiquitinated MEF2A by neurotoxins induces the characteristics of Parkinson's disease in an animal model, indicating that accumulation of inactive MEF2A is also one of the causes of neurodegenerative diseases." (PMID 37008050, 2023). "Among these factors, CTCF, MEF2A, and STAT3 have been associated with Alzheimer’s, Huntington’s, and Parkinson’s diseases." (PMID 34720873, 2021). "The myocyte enhancer factor 2A (MEF2A) promoted neuronal cell apoptosis in vitro and in vivo experimental models of Parkinson’s disease and some of its genetic variants associated with an increased risk of late-onset AD." (PMID 34720873, 2021). "Reducing Mef2a activity was shown to be involved in Parkinson's disease features in model animals." (PMID 33628784, 2021).
endothelial dysfunction (3 papers, 2022 to 2023). In vascular diseases, endothelial dysfunction is a systemic pathological state of the endothelium (the inner lining of blood vessels) and can be broadly defined as an imbalance between vasodilating and vasoconstricting substances produced by (or acting on) the endothelium. "MiR-135b-5p in vitro inhibition demonstrated an upregulation of the transcription factor Mef2a, which is associated with endothelial dysfunction and differentiation of vascular smooth muscle cells." (PMID 37833432, 2023).
leukemia (3 papers, 2022 to 2023). A malignant (clonal) hematologic disorder, involving hematopoietic stem cells and characterized by the presence of primitive or atypical myeloid or lymphoid cells in the bone marrow and the blood. "MEF-2 isoforms, mainly MEF-2A and -2C, have also been implicated in various leukemias and lymphomas, as well as virus infection." (PMID 36620051, 2022).
melanoma (3 papers, 2017 to 2023). A malignant, usually aggressive tumor composed of atypical, neoplastic melanocytes. "We further demonstrated that two high-level screened HRR-associated enhancers are crucial in sustaining MEF2A and PTEN tumor-suppressive potential in melanoma cells." (PMID 37904237, 2023). "By combining genomic, functional, and clinical evidence, we discovered that the critical enhancer, E_349, within a super enhancer region, plays a tumor-suppressive role in melanoma through modulation of MEF2A expression." (PMID 37904237, 2023). "However, MEF2A is poorly characterized and has been rarely studied in melanoma." (PMID 37904237, 2023). "Utilizing extensive functional validation experiments, we demonstrate that a super enhancer element could modulate melanoma cell proliferation by targeting MEF2A, and another distal enhancer is able to sustain PTEN tumor-suppressive potential via long-range interactions." (PMID 37904237, 2023). "In-depth functional assays demonstrated that the two highest ranked enhancers are critical in sustaining MEF2A and PTEN tumor-suppressive potential in melanoma cells." (PMID 37904237, 2023). "For instance, MEF2A, EMP2, ZNF440, PIGL, FRMD4B, and HIF3A are not only downregulated in TCGA-SKCM melanoma samples but also essential for restraining tumor growth in CRIPSR KO screens." (PMID 37904237, 2023).
Sepsis (3 papers, 2021 to 2023). Sepsis is defined as life-threatening organ dysfunction caused by a dysregulated host response to infection. "miR-144-3P was shown to have anti-tumor properties by inhibiting the expression of MEF2A, while miR-194-5p delays the progression of sepsis by down-regulating MEF2A." (PMID 37008050, 2023). "According to the authors, the long non-coding RNA MIR155HG facilitates sepsis progression by upregulating MEF2A." (PMID 34680414, 2021). "This three-TF axis has not been directly linked to sepsis in the literature, except by MEF2A." (PMID 34680414, 2021). "Our results give direction on how sepsis master regulators work coordinately in disease progression, especially MEF2A, TRIM25, and RFX2, with potential implications in pediatric sepsis prognosis." (PMID 34680414, 2021).
Anxiety (2 papers, 2012 to 2023). Intense feelings of nervousness, tension, or panic often arise in response to interpersonal stresses. "Our data further suggest that activation of MEF2A via dephosphorylation at Ser408 is crucial to drive alternative splicing of Crfr2α, as this occurred only in the male 10 ng/h group and parallel to the increase in anxiety." (PMID 34035479, 2023). "In conclusion, our study shows that chronic OXT dose-dependently enhances anxiety-like behavior in males and females, which involves the activation of the transcription factor MEF2A and subsequent alternative splicing of Crfr2α mRNA into the anxiogenic soluble form in male rats." (PMID 34035479, 2023). "In conclusion, chronic central infusion of high OXT results in MEF2A activation in the PVN of male rats, and increased anxiety-related behavior." (PMID 34035479, 2023). "However, in females, chronic OXT-induced anxiety appears to be mediated independent of MEF2A activation and sCRFR2α production." (PMID 34035479, 2023).
autism (2 papers, 2017 to 2023). Persistent deficits in social interaction and communication and interaction as well as a markedly restricted repertoire of activity and interest as well as repetitive patterns of behavior. "Experiments with a mouse model show that deletion of Mef2a can lead to behaviors related to autism and drug addiction." (PMID 37008050, 2023). "In mice, deletion of Mef2a,c, and/or d leads to behaviors relevant to autism and drug addiction and alterations in learning and memory." (PMID 28901289, 2017). "Therefore, MEF2A is believed to determine the responsiveness of neuronal cells to OT and to be involved in the pathological mechanism of autism." (PMID 37008050, 2023).
autism spectrum disorder (2 papers, 2016 to 2024). A spectrum of developmental disorders that includes autism, and Asperger syndrome. "Similarly, conditional deletion of MEF2C, but not MEF2A and MEF2D, is linked with altered memory formation and synaptic plasticity in the hippocampus, and MEF2C-related aberrations have been implicated in the development of autism-spectrum disorders (ASDs)." (PMID 38796067, 2024).
brain ischemia (2 papers, 2021 to 2024). Diminished or absent blood supply to the brain caused by obstruction (thrombosis or embolism) of an artery resulting in neurologic damage. "Studies have shown that inhibition of MEF2A transcriptional activity can promote neuronal apoptosis, but its role and regulatory mechanism in cerebral ischemia-reperfusion injury model are still unclear." (PMID 33584197, 2021). "Therefore, we speculated that ERK5/MEF2A signaling pathway may be involved in the ER stress pathway and apoptosis process of cerebral ischemia-reperfusion injury." (PMID 33584197, 2021). "These proteins include BPTF and MEF2C, which govern microglial homeostatic responses; MEF2A, which promotes autophagy; and ZEB1, which mediates protective effects after brain ischemia (Set 2)." (PMID 38178204, 2024). "The study aimed to estimate the efficacy of dexmedetomidine and Netrin-1 combination therapy against ERS-induced apoptosis after cerebral ischemia injury in vivo and in vitro, and whether the mechanism is related to the ERK5/MEF2A pathway." (PMID 33584197, 2021).
depression (2 papers, 2012 to 2023). "Moreover, TBP and MEF2A were common transcription factors involved in three shared genes, which may play a significant role in ED and depression." (PMID 38111702, 2023). "The 15 target genes include DYNLT1, GCH1, TOR1B, DISC1, MEF2A and ST3GAL5 that to date were never related to an IFN-α regulation while all of them have been described in association with brain development or depression." (PMID 22701688, 2012).
fibrosis (2 papers, 2016 to 2019). the formation of excess fibrous connective tissue in an organ or tissue in a reparative or reactive process. "This study sought to identify whether inhibition of Myocyte enhancer factor 2A (MEF2A) alleviates cardiac fibrosis by partially regulating Endothelial-to-mesenchymal transition (EndMT)." (PMID 27105518, 2016). "To correlate MEF2 levels and fibrogenic response in vivo, we examined the expression of MEF2A and α-SMA in the rat liver using a well-established model of DMN-induced fibrosis." (PMID 31031620, 2019).
Hyperglycemia (2 papers, 2016 to 2019). An increased concentration of glucose in the blood. "In diabetic mouse models, MEF-2A knockdown in cardiac fibroblasts led to significant reduction of hyperglycemia-induced cardiofibroblast proliferation, myofibroblast differentiation, and matrix metalloprotease (MMP) and collagen activity, as well as improved cardiac function and collagen deposition." (PMID 31105874, 2019). "Thus, hyperglycemia leading to MEF2A activation is an essential mechanism that may contribute to myocardial remodeling and fibrosis in DCM, and silencing MEF2A may have therapeutic potential in ameliorating these processes." (PMID 27105518, 2016).
lupus (2 papers, 2022 to 2023). "By the way, DNA binding sites for MEF2A and BCL6 were significantly enriched in systemic lupus erythematosus susceptibility loci." (PMID 38255677, 2023). "Indeed, most Nr4a1-controlling genes (Grin1, Creb3l3, Mef2a, Mef2c, and Mef2d) were reduced in the lupus hippocampus, as revealed by sequencing assays." (PMID 35177587, 2022).
myotonic dystrophy (2 papers, 2019 to 2023). An inherited progressive disorder affecting the muscles. "Dysregulated expression and splicing of Mef2a, Mef2c and Mef2d genes occur in several neuromuscular disorders, including Becker syndrome and myotonic dystrophy (DM), which is characterized by the expression of MEF2 embryonic isoforms." (PMID 37894843, 2023).
oral squamous cell carcinoma (2 papers, 2022). "MEF2A may also promote the transcriptional activity of other factors, thus promoting stem-like properties of oral squamous cell carcinoma and playing an important role in the development of HNSC." (PMID 36204311, 2022).
Pancreatic Cancer (2 papers, 2017 to 2025). "For illustrating how key pfsSNVs can be prioritized further, we provide a use case where we performed survival analysis showing that a loss of phosphorylation site pfsSNV at position 105 in MEF2A is significantly associated with decreased pancreatic cancer patient survival rate." (PMID 28176830, 2017).
type 1 diabetes (2 papers, 2016 to 2020). "In vivo, MEF2A mRNA and protein were significantly increased in the STZ model of type 1 diabetes, with MEF2A knockdown attenuating cardiac fibrosis with improved cardiac function." (PMID 32024054, 2020).
type 2 diabetes (2 papers, 2022 to 2025). "A 6-month training study in males with and without a family history of type 2 diabetes showed decreased DNA methylation of genes with known function in muscle and type 2 diabetes, including MEF2A, RUNX1, NDUFC2, and THADA, decreased after exercise." (PMID 35323665, 2022).
viral infection (2 papers, 2020 to 2023). "Our analysis of three distinct omics data sets has allowed identification of cellular processes that MEF2A may serve to regulate in the heart including necrosis, apoptosis, response to viral infection and enlargement of the heart." (PMID 37019881, 2023).